CALY (calcyon neuron specific vesicular protein)
Description:
Interacts with clathrin light chain A and stimulates clathrin self-assembly and clathrin-mediated endocytosis.
Synonyms: DRD1IP; CALCYON; NSG3
Tractability: Antibody: its Gene Ontology location is reachable by antibodies, with high confidence; UniProt places it where antibodies can reach, with medium confidence; UniProt predicts a signal peptide or a membrane-spanning region.
Gene: Protein-coding gene on chromosome 10 (133,324,072 to 133,336,980, reverse strand). Ensembl gene ENSG00000130643.
Subcellular location: Cytoplasmic vesicle membrane; Cell membrane
Gene Ontology:
Molecular function: clathrin light chain binding; protein binding
Biological process: clathrin coat assembly; positive regulation of endocytosis; endosomal transport; postsynaptic neurotransmitter receptor internalization
Cellular component: cytoplasmic vesicle; plasma membrane; postsynaptic endocytic zone; endosome; membrane; cytoplasmic vesicle membrane; glutamatergic synapse
Genetic constraint (gnomAD): Loss-of-function variants: 10 observed, 10.85 expected, observed/expected ratio (o/e) 0.92, 90% interval 0.57 to 1.55. The upper end of that interval is the gene's LOEUF score, 1.55, which puts it in group 6 of 6, group 1 being the genes least tolerant of losing a copy. Missense variants: 251 observed, 225.88 expected, observed/expected ratio (o/e) 1.11, 90% interval 1 to 1.23. Synonymous variants: 124 observed, 100.83 expected, observed/expected ratio (o/e) 1.23, 90% interval 1.06 to 1.43.
Homologues: Orthologues: chimpanzee CALY (99% identical), macaque CALY (98% identical), guinea pig CALY (88% identical), rabbit CALY (82% identical), rat Caly (82% identical), mouse Caly (81% identical), pig CALY (76% identical), zebrafish caly (31% identical). Paralogues in human: NSG1 (33% identical), NSG2 (26% identical).
Diseases named in the same sentence as CALY in open-access papers:
CALY is named in the same sentence as 3 diseases in open-access papers, as found by Europe PMC text mining. Sharing a sentence is not in itself a finding about the gene and the disease.
CALY shares sentences with these, for which no sentence is quoted: Anxiety (4 papers); memory impairment (1); schizophrenia (1).